ALDH1A2 (aldehyde dehydrogenase 1 family member A2)
Diseases named in the same sentence as ALDH1A2 in open-access papers (continued):
Sharing a sentence is not in itself a finding about the gene and the disease.
prostate carcinoma (14 papers, 2014 to 2025). A carcinoma that arises from epithelial cells of the prostate gland. "Pooled analysis of 42 prostate cancer gene expression datasets revealed that ALDH1A2 expression was significantly lower in prostate cancer tissues and higher expression was associated with better patient prognosis." (PMID 39781359, 2025). "We have shown that SNPs in ALDH1A2 are associated with altered prostate cancer‐specific mortality in a case‐only analysis." (PMID 27643404, 2017). "RA signaling has been shown to crosstalk with Wnt/β-catenin signaling and Aldh1a2 has also been identified as a tumor suppressor in prostate cancer, loss of which is an early event in the disease." (PMID 24672774, 2014). "In addition, ALDH1A2 expression was associated with increased immune cell infiltration into the prostate cancer microenvironment." (PMID 39781359, 2025). "Furthermore, higher ALDH1A2 expression was positively associated with immune cell infiltration, suggesting a protective role in prostate cancer progression." (PMID 39781359, 2025). "Through a discovery-replication design, our study provides compelling evidence that genetic variants in the ALDH1 family, particularly ALDH1A2 rs16939929 A>G, may serve as promising prognostic biomarkers for prostate cancer." (PMID 39781359, 2025). "Functional studies suggest that this variant may influence prostate cancer progression through its association with ALDH1A2 expression, which is linked to cell adhesion pathways." (PMID 39781359, 2025). "A pooled analysis of 11 studies revealed that higher ALDH1A2 expression was associated with better prognosis (HR=0.43, 95% CI=0.28-0.67, P<0.001), indicating that ALDH1A2 may play a tumor-suppressive role in prostate cancer progression." (PMID 39781359, 2025). "In this study, we explored the clinical significance and function of ALDH1A2 expression in prostate cancer using bioinformatic and functional analyses." (PMID 39781359, 2025). "In prostate cancer, ALDH1A2 is frequently silenced by promoter hypermethylation, leading to decreased RA synthesis, which is essential for normal cellular differentiation." (PMID 39781359, 2025). "ALDH1A2 expression was significantly lower in prostate cancer tissues compared to normal tissues (SMD=-0.97, 95% CI=-1.18 to -0.77, P<0.001)." (PMID 39781359, 2025). "To assess the clinical significance of ALDH1A2 expression in patients with prostate cancer, we analyzed 2,510 prostate cancer samples and 1,004 normal prostate specimens from 36 public datasets." (PMID 39781359, 2025). "Restoration of ALDH1A2 expression and RA treatment have been shown to inhibit prostate cancer cell growth by inducing differentiation and reducing proliferation." (PMID 39781359, 2025). "Subsequent functional analyses, including gene ontology and pathway enrichment analyses, provided insights into the biological mechanisms by which ALDH1A2 influences prostate cancer progression." (PMID 39781359, 2025). "To investigate the biological significance of ALDH1A2 in prostate cancer, we identified genes that correlated with ALDH1A2 expression in the TCGA-PRAD dataset." (PMID 39781359, 2025). "In conclusion, ALDH1A2 rs16939929 is a significant predictor of BCR-free survival in prostate cancer, potentially through its effects on the gene expressions of ALDH1A2 and cell adhesion molecules." (PMID 39781359, 2025). "Although the ALDH1 family plays complex roles in cancer biology, ALDH1A2 has been shown to be downregulated in several tumor types, including prostate cancer, according to TCGA database." (PMID 39781359, 2025). "Given the known association between ALDH1 family members and the tumor immune microenvironment, we explored the relationship between ALDH1A2 expression and immune cell infiltration in prostate cancer." (PMID 39781359, 2025). "The ALDH1A2 gene promoter was significantly hypermethylated in primary prostate cancer as compared with normal prostate epithelium, which expressed ALDH1A2." (PMID 36768694, 2023).
prostate carcinoma (continued). "Aldehyde dehydrogenase 1 family member A2 (ALDH1A2) has been reported to be down-regulated in the early stages of human prostate cancer, and can be used as a candidate tumor suppressor gene for prostate cancer." (PMID 35132081, 2022). "An immunohistochemical analysis of ALDH1A2 expression displayed low cytoplasmic staining in human prostate cancer paraffin sections relative to normal human prostate tissues, presumably due to its promoter hypermethylation in PCa samples." (PMID 34572930, 2021). "In prostate cancer, retinaldehyde dehydrogenase 2 (ALDH1A2) is silenced by locus hypermethylation and acts as a tumor suppressor." (PMID 31805753, 2019). "As a case study, we applied this pipeline to systematically analyze the role of ALDH1A2 in prostate cancer (PCa)." (PMID 28361034, 2017). "ALDH1A2 was reported as a candidate tumor suppressor in prostate cancer, downregulated on early stage of human prostate cancer." (PMID 27015121, 2016). "Reduced ALDH1A2 levels were reported previously in tumor cell lines, a mouse tumor model and tumor specimens of prostate cancer patients." (PMID 26634247, 2015). "Moreover, the expression levels of these cell adhesion molecules were significantly associated with improved patient survival, further supporting the potential protective role of ALDH1A2 in prostate cancer progression through these cell adhesion molecules." (PMID 39781359, 2025). "However, further research is required to fully understand the molecular mechanisms by which ALDH1A2 influences prostate cancer." (PMID 39781359, 2025). "Additionally, ALDH1A2 expression was significantly lower in prostate cancer tissues than in normal tissues, and higher ALDH1A2 expression correlated with better patient prognosis." (PMID 39781359, 2025). "ALDH1A2 is widely recognized as a tumor suppressor gene in prostate cancer." (PMID 34572930, 2021). "Three single nucleotide polymorphisms (SNP) of ALDH1A2 were significantly associated with a more prolonged PCa survival but not the diagnosis of prostate cancer." (PMID 34572930, 2021). "Moreover, high ALDH1A2 expression correlates with increased infiltration of anticancer immune cells, suggesting that ALDH1A2 may exert a tumor-suppressive effect in prostate cancer by modulating cell adhesion and anticancer immunity." (PMID 39781359, 2025). "Histological studies have compared the expression of ALDH1s in primary prostate cancer and normal prostate epithelium and confirmed a lack of expression of ALDH1A2 in primary prostate cancer." (PMID 36768694, 2023). "Additionally, higher ALDH1A2 expression was positively correlated with the infiltration of all measured immune cells, including B cells, CD8+ T cells, CD4+ T cells, macrophages, neutrophils, and dendritic cells, in prostate cancer." (PMID 39781359, 2025). "For prostate cancer, and as above, this could reflect a reduced/lack of activity of ALDH1A1 and ALDH1A2, which oxidise all-trans-retinaldehyde to ATRA." (PMID 36768694, 2023).
breast carcinoma (9 papers, 2015 to 2022). "Furthermore, high ALDH1A2 transcription levels correlated with improved overall survival in breast cancer patients." (PMID 31615043, 2019). "Furthermore, high ALDH1A2 transcript levels correlated with improved overall survival of breast cancer patients." (PMID 26634247, 2015). "Reduced protein levels of recombinant aldehyde dehydrogenase 1 family, member A2 (ALDH1A2), a key player in the retinoic acid (RA) pathway and retinoid metabolism, have been reported in human prostate and breast cancer." (PMID 36437918, 2022). "Human U87MG glioblastoma and human HCT116 colorectal cancer are labelled as ALDH1A3+ cell lines, HEK293T as ALDH1A2+ cell line, human foetal astrocytes (hASTRO) and CCD-18Co human colon fibroblasts as ALDH1A1+ cell line and 4T1 mammary carcinoma as triple negative ALDH1A subfamily." (PMID 33478031, 2021).
congenital heart disease (8 papers, 2009 to 2024). A heart disease that is present at birth. "Two missense mutations, A151S and I157T, have been identified for the human ALDH1A2 enzyme, where these two mutations are strongly associated with congenital heart disease." (PMID 36450447, 2023). "Vital for retinoic acid synthesis during early development, ALDH1A2 has previously been demonstrated in animal models to have a strong association with congenital heart disease and diaphragmatic hernia, two key elements comprising pentalogy of Cantrell." (PMID 24377748, 2013). "Since conversion of retinaldehyde to RA by retinaldehyde dehydrogenase type II (ALDH1A2, a.k.a RALDH2) is critical for cardiac development, we screened patients with congenital heart disease (CHDs) for genetic variation at the ALDH1A2 locus." (PMID 19886994, 2009). "A number of variations in ALDH1A2 have been described in human patients with congenital heart disease (CHD), but none of them have been confirmed as significant modifiers of the risk of CHD in humans." (PMID 37938355, 2024).
lung cancer (7 papers, 2012 to 2023). A malignant neoplasm involving the lung. "Other groups have detected ALDH1A1, ALDH1A2, ALDH3A1, and ALDH2A1 in lung cancers which were shown to have an association with chemoresistance." (PMID 24884875, 2014). "Controversially, an in vitro study showed that K562 leukemia and H1299 lung cancer cell with ALDH1A2 overexpression exhibited higher cell proliferation rates, higher clonal efficiency, and increased drug resistance to 4-hydroperoxycyclophosphamide and doxorubicin." (PMID 27015121, 2016). "Similarly, inhibition of ALDH1A2 and ALDH2 by DEAB showed an obvious concentration dependence in K562 leukaemia cells and H1299 lung cancer cells." (PMID 36651035, 2023). "Hypermethylation and/or the downregulation of some of the genes identified in our study (e.g. ALDH1A2, HOXA5, MT1E, SOX17) have been reported in other cancers, but not yet in lung cancer." (PMID 22768131, 2012).
neuroblastoma (5 papers, 2015 to 2023). Neuroblastoma (NB) is the most common solid, extracranial childhood tumor. "It was shown that the expression of ALDH1A2 isoform significantly correlates with poor prognosis in neuroblastoma patients and is associated with the resistance of neuroblastoma cells to 13cisRA." (PMID 29301374, 2018). "ALDH1A2 expression was also associated with increased neuroblastoma growth in vivo, resistance to 13-cis-retinoic acid and worse prognosis in neuroblastoma patients." (PMID 26729169, 2015). "ALDH1A2 played a role in conferring resistance to 13-cis-retinoic acid (13-cis-RA) in neuroblastoma cells." (PMID 37954205, 2023). "We next focused our analyses on the expression of ALDH genes related to neuroblastoma CSCs, including ALDH1A2 and ALDH1A3." (PMID 32483461, 2020). "Analysis of the gene expression dataset from the TARGET study revealed that high expression of both ALDH1A2 and ALDH1A3 was associated with a worst outcome for neuroblastoma patients (n= 33/135 and 72/135 for ALDH1A2 and ALDH1A3 respectively)." (PMID 32483461, 2020). "Increased aldehyde dehydrogenase (ALDH) activity has been associated with CSCs in several cancers, including neuroblastoma, where ALDH activity and expression of certain ALDH isoforms (i.e., ALDH1A2, ALDH1L1, ALDH3B2) were associated with sphere and colony formation." (PMID 26729169, 2015). "Our data revealed that ALDH1A1 and ALDH1A3 mRNA expression positively correlates with c-MYC gene expression in the neuroblastoma patient samples, and siRNA-mediated c-MYC knockdown inhibited expression of ALDH1A2 and ALDH1A3 genes in the MYCN-amplified neuroblastoma cells." (PMID 32483461, 2020). "Several studies have demonstrated that neuroblastoma contains a cell population having stem-cell like properties with enhanced expression of CSC markers including CD117, CD133, OCT4 and ALDH activity attributed to the expression of ALDH1A2 and ALDH1A3 proteins 13-16." (PMID 32483461, 2020).
colitis (4 papers, 2023 to 2024). Inflammation of the colon. "Loss of ALDH1a2 expression via the CD11c-specific deletion of Rbtj led to colitis as inducible Treg differentiation was lost." (PMID 39133222, 2024). "Cometabolism of L. intestinalis ALDH and host ALDH1A2 contributed to elevated biosynthesis of retinoic acid (RA), which accounts for the anti‐colitis effect in RAR‐α ‐mediated way." (PMID 37983567, 2023). "Engineering of DCs to overexpress ALDH1a2 suppresses experimentally induced colitis." (PMID 39133222, 2024).
glioblastoma (4 papers, 2021 to 2025). The most malignant astrocytic tumor (WHO grade IV). "Notably, ALDH1A2 expression was significantly reduced in 17 TCGA tumor types, including bladder, breast, cervical, colon, esophageal, glioblastoma, head and neck, kidney, lung, prostate, rectum, stomach, thyroid, and endometrial cancers, when compared to adjacent normal tissues (data not shown)." (PMID 39781359, 2025).
glioma (4 papers, 2017 to 2022). A benign or malignant brain and spinal cord tumor that arises from glial cells (astrocytes, oligodendrocytes, ependymal cells). "Besides, ALDH1A1 and ALDH1A2 have been documented as glioma migration-associated genes, while ALDH1A1 also participated in GBM resistance to temozolomide." (PMID 35116021, 2021). "Sanders and co-workers demonstrated increased expression of ALDH1A2 in GBM compared to the expression detected in low-grade gliomas and upregulation of ALDH1A2 expression upon GBM recurrence." (PMID 36010607, 2022). "Additionally, GBM samples showed higher expression of ALDH1A2 when compared to low-grade gliomas (LGG), and this expression was increased upon tumor recurrence both at the gene and protein levels." (PMID 34572134, 2021). "In the LGG cohort from the TCGA dataset, ALDHs including ALDH2, ALDH6A1, ALDH5A1, ALDH9A1, ALDH1A1 were upregulated in WHO grade II gliomas while the increased expression of ALDH16A1, ALDH3B1, ALDH3A2, ALDH1A2, ALDH3A1 was found in WHO III grade gliomas." (PMID 35116021, 2021).
Hypertension (4 papers, 2011 to 2024). The presence of chronic increased pressure in the systemic arterial system. "Single-nucleus RNA sequencing data show that ALDH1A2 mRNA expression in PECs is diminished in patients with chronic kidney disease associated with diabetes, hypertension and polycystic kidney disease." (PMID 39360029, 2024). "Aldh1a2 expression in PECs is substantially repressed in a chronic kidney disease mouse model combining diabetes, hypertension, and partial nephrectomy and is moderately repressed in mouse models of focal segmental glomerulosclerosis and diabetic nephropathy." (PMID 39360029, 2024). "ScRNA-seq and snRNA-seq clinical studies also show diminished ALDH1A2 mRNA expression in PECs in patients with CKD, including those with diabetes, hypertension and ADPKD." (PMID 39360029, 2024).
osteoarthritis (4 papers, 2018 to 2022). A noninflammatory degenerative joint disease occurring chiefly in older persons, characterized by degeneration of the articular cartilage, hypertrophy of bone at the margins and changes in the synovial membrane. "We found strong evidence for co-localisation of five osteoarthritis signals with cartilage molQTLs for ALDH1A2, NPC1, SMAD3, FAM53A and SLC44A2." (PMID 33637762, 2021). "Several osteoarthritis GWAS signals were found to co-localise with eQTLs in only 1 or 2 of 53 tissues (e.g. ALDH1A2: ovary and tibial artery, SMAD3: skeletal muscle; SLC44A2: adrenal gland), without clear transferability of results to disease-relevant tissue." (PMID 33637762, 2021). "Although the lead ALDH1A2 SNP itself has not been identified in previous GWAS, other independent variants (R2 < 0.6) at the same locus (e.g., rs3204689) have been found to be associated with osteoarthritis." (PMID 33510174, 2021). "For seven genes (ALDH1A2, CHMP1A, CRADD, FAM53A, LTBP1, RPP25, and TGFA), we found evidence that GWAS signals for osteoarthritis colocalize with mQTLs in these genes and are additionally associated with gene expression levels in the same tissue." (PMID 35679866, 2022). "We found evidence (MR p < 0.05) for a causal effect of methylation on gene expression levels for two genes (ALDH1A2 and RPP25) in low-grade osteoarthritis cartilage and one gene (LTBP1) in high-grade osteoarthritis cartilage." (PMID 35679866, 2022). "We found such an eQTL effect below nominal significance levels for five genes in low-grade osteoarthritis cartilage (ALDH1A2, CHMP1A, FAM53A, RPP25, and TGFA), two genes in high-grade osteoarthritis cartilage (FAM53A and LTBP1), and one gene in synovium (CRADD)." (PMID 35679866, 2022).
schizophrenia (4 papers, 2013 to 2024). A major psychotic disorder characterized by abnormalities in the perception or expression of reality. "In a methylome-wide association study of schizophrenia, ALDH1A2 was identified to be the second-most significant site." (PMID 37029353, 2023). "ALDH1A2, encodes an enzyme for astrocyte-derived retinoic acid, is a key neuronal morphogen with relevance for schizophrenia." (PMID 37029353, 2023). "In addition, a study in a Chinese population reported a positive association between ALDH1A2 SNPs and schizophrenia." (PMID 33276438, 2020). "As to the co-treatment condition, an interesting observation in the miRNA-mRNA network was the direct interaction of ALDH1A2 with three schizophrenia-related miRNAs: hsa-miR-137, hsa-miR-542-3p, and hsa-miR-338-3p." (PMID 38792584, 2024). "Seven genes were investigated and involved in the synthesis, degradation and transportation of RA, ALDH1A1, ALDH1A2, ALDH1A3, CYP26A1, CYP26B1, CYP26C1 and Transthyretin (TTR), for their roles in the development of schizophrenia." (PMID 24564241, 2013).
Alzheimer disease (3 papers, 2012 to 2021). A progressive, neurodegenerative disease characterized by loss of function and death of nerve cells in several areas of the brain leading to loss of cognitive function such as memory and language. "In particular, genes such as Col1a1 Col1a2, Fmod, Ptgds, and Aldh1a2 are induced by exercise training and have been found to prevent hippocampal ageing in an Alzheimer’s disease model of animals with premature ageing." (PMID 31551509, 2019).
Barrett esophagus (3 papers, 2015 to 2018). Esophageal lesion lined with columnar metaplastic epithelium which is flat or villiform. "Meta-analysis of all data identified another SNP associated with BE and esophageal adenocarcinoma: rs3784262, within ALDH1A2 (OR = 0.90; 95% CI: 0.87–0.93; P = 3.72 × 10−9)." (PMID 25447851, 2015).
hand osteoarthritis (3 papers, 2018 to 2025). "In addition, non-coding ALDH1A2 variants reduce ALDH1A2 expression in chondrocytes and contribute to severe hand osteoarthritis in adults." (PMID 39360029, 2024).
inflammatory bowel disease (3 papers, 2018 to 2024). A spectrum of small and large bowel inflammatory diseases of unknown etiology. "In this context, it is interesting to note that IEC isolated from patients with the inflammatory bowel disease, Crohn’s disease, have a highly reduced ability to induce Treg-cell-promoting DC, as well as reduced Aldh1a2 and Tgfb1 expression as compared to healthy controls." (PMID 34084164, 2021).
myocardial infarction (3 papers, 2012 to 2025). Gross necrosis of the myocardium, as a result of interruption of the blood supply to the area, as in coronary thrombosis. "To investigate whether retinoic acid transporting and metabolizing proteins are induced after myocardial infarction, we extracted proteins from infarcted and sham operated hearts one week after coronary artery ligation for western blotting with antibodies against RBP1 and ALDH1A2." (PMID 23028599, 2012).